BRCA1 (BRCA1 DNA repair associated)
Diseases named in the same sentence as BRCA1 in open-access papers (continued):
Sharing a sentence is not in itself a finding about the gene and the disease.
tumor (continued). "The BRCA1 and BRCA2 genes play an important role in maintaining genomic integrity and tumor suppression through the mediation of DNA repair by homologous recombination and reactivation of replication." (PMID 33525353, 2021). "The study suggested the cooperation of EZH2 and BRCA1 in regulating ALDH1A1 expression, PCa stem cells, and tumor radioresistance, and the genetic silencing of EZH2 alone or in combination with BRCA1 knockdown decreased the ALDH1A1 level." (PMID 34572930, 2021). "Luc-4T1 cells, either alone or pre-mixed with BRCA1+/− or BRCA1+/+ iMSCs, were injected into the mammary fat pads of NOD-SCID mice; measurements of tumor volume were taken over the next 18 days." (PMID 33513753, 2021). "Many mouse models have been generated to study the function of BRCA1, BRCA2, and PALB2 in development and tumor suppression." (PMID 33893322, 2021). "Platinum-based chemotherapy was also shown to enhance HR as a DNA damage repair reaction, potentially upregulating BRCA1/2 and RAD51, so that an additional effect on tumor cell death of thiostrepton can be assumed." (PMID 33668819, 2021). "BRCA1 expression was higher in cancerous mammary glands than in noncancerous breast epithelial tissues, whereas PINK1 and Parkin expressions were lower in tumor tissues." (PMID 33888730, 2021). "Consistently, there was a significant decrease in BRCA1 protein level and increase in γ-H2AX level in the GSK3β KO tumor xenografts treated with simmiparib." (PMID 33589588, 2021). "While the prevalence of germline BRCA1/2 PV is reported to be 10–20% in women with HGSC, BRCA1/2 PVs are identified in 15–30% of tumor samples." (PMID 33030818, 2021). "Tumour BRCA1/BRCA2 testing in 116 Manchester cases identified 7 (6%) BRCA1 and 5 (4.3%) BRCA2 somatic PVs as well as 1 (0.9%) BRCA1 and 1 (0.9%) BRCA2 somatic VUS each." (PMID 34503154, 2021). "Using the new NSG-Pro recipient strain with ER+ PDX models, we uncovered evidence of actionable somatic BRCA1/2 pathway disruption in tamoxifen-resistant, isogenic PDX tumor sublines." (PMID 34524841, 2021). "Treatment of BRCA1 mutant BLBC patient-derived xenograft models with combination PARP and CDK2 inhibition led to tumor regression and increased survival." (PMID 34465787, 2021). "In summary, a total of 33/88 (38%) of tumours showed an alteration in an HRR-related gene, of which 19 were BRCA1/2 and 14 were additional genes." (PMID 34680387, 2021). "Second, tumor-only sequencing was performed, and it was difficult to differentiate somatic mutations from those with germline origin, which might hinder the clinical applicability, particularly for PARP inhibitors, as germline mutation of BRCA1 or BRCA2 is the prerequisite for synthetic lethality." (PMID 34203389, 2021). "Tumor samples were immunohistochemically stained for RAD51, γH2AX, conjugated ubiquitin, and BRCA1 foci." (PMID 33670893, 2021). "There were six BRCA1/BRCA2 PVs that showed discordance between germline and tumour testing, five in the NELCN cases and one from the Manchester cases, comprising 10.3% of all germline PVs." (PMID 34503154, 2021). "Further, PLK1 phosphorylates BRCA1 thus impairing its involvement in homologous recombination, and reported PLK1 expression is higher in TNBC than in both healthy cells and benign tumours." (PMID 33807045, 2021). "Further and more in-depth studies are required to define the complementary functions of BRCA1 and PALB2/BRCA2 in tumor suppression." (PMID 33893322, 2021). "It is known that in certain cases presence of germline BRCA1/2 mutations may not be related to tissue carcinogenesis either due to persistence of the wild-type allele (no Loss of Heterozygosity) or due to reversing mutations in the tumor." (PMID 34898566, 2021).
tumor (continued). "BRCA1 and BRCA2 are tumour suppressor genes that produce the key enzymatic pathways for homologous recombination-mediated repair of double-stranded DNA breaks." (PMID 33671468, 2021). "Secondly, as a tumor suppressor, FOXP3 represses many key target genes in cancer development and progression, such as HER2/ERBB2, BRCA1, SKP2, and CD44, providing a strong link between FOXP3 and cell cycle regulation as well as FOXP3 and DNA repair system." (PMID 34768829, 2021). "Some studies have shown that overexpression and binding of the transcription factor YY1 to the BRCA1 promoter inhibits the proliferation and focus formation of MDA-MB-231 cells and inhibits the growth of MDA-MB-231 tumor in nude mice." (PMID 34876062, 2021). "In the BRCA1 R1443* mutant PDX, single agent olaparib led to reduced tumor burden and increased overall survival." (PMID 34465787, 2021). "Consequently, oncologists speaking to individuals about tumor BRCA1/2 testing can do so in the context of therapeutic implications, with more detailed informed consent discussions around hereditary testing occurring at the time of genetic counseling following a positive tumor test." (PMID 33030818, 2021). "BRCA1 and BRCA2 (loci 17q21 and 13q12.3, respectively) are major tumor-suppressor genes involved in DNA double-stranded break repair by homologous recombination (HRR)." (PMID 34298749, 2021). "Antiangiogenic therapy induces cell hypoxia, which leads to downregulation of HR repair genes (BRCA1, BRCA2, and RAD51), increasing tumor sensitivity to PARPis." (PMID 34912215, 2021). "Gene alterations in BRCA1, BRCA2, and ATM were detected in 2.0, 10.7, and 8.8%, respectively, of cfDNA samples and in 1.6, 8.2, and 5.8%, respectively, of tumour tissue samples." (PMID 33630412, 2021). "In addition to evaluating differential distribution of age, sex, tumor stage, metastasis score, tumor size/subtype, and race across BRCA1 mRNA-low versus -high groups, we also identified genes whose expression correlated with BRCA1 mRNA expression across tissue type or in a tissue-specific manner." (PMID 34611475, 2021). "As PALB2 exhibits functions in the BRCA1/2-RAD51-dependent homologous DNA recombination repair pathway, we sought to use ex vivo functional screening to explore sensitivity of the tumor cells to therapeutic targeting of DNA repair." (PMID 34084283, 2021). "Other examples from this study include well-described tumor-promoting genes such as SRSF2, DNMT3A, ATM, BRCA1 and PKM, for which Tax- and HBZ-alternative splicing events are now associated with ATLL for the first time." (PMID 34543356, 2021). "First, for the patients with germline BRCA1/2 mutation who were sensitive to PARPis, human somatic cells with theoretically subsequent BRCA1/2 mutation were not globally harmed by PARPis, which meant that somatic and tumor cells demonstrated varied sensitivity to PARPis." (PMID 34869593, 2021). "Of the patients bearing a tumor with BECN1 and BRCA1 shallow deletion, 105 (60.4%) of patients were sensitive, 47 (27%) were resistant and 22 (12.6%) developed early resistance." (PMID 33670664, 2021). "NPC xenograft studies demonstrated that MGMT inhibition combined with CDDP treatment reduced tumor size and downregulated RAD51 expression and BRCA1 phosphorylation." (PMID 33397362, 2021). "miR483-3p was found to target DLC-1, BRCA-1 and PUMA which are a candidate tumor repressor, a tumor repressor and an apoptosis modulator, respectively." (PMID 34593874, 2021). "The primary treatment-naïve tumor was extracted in the diagnosis and had MCL1 and NOTCH3 amplifications, and a BRCA1 deletion." (PMID 34680239, 2021). "By carefully checking the expression patterns of MRC2 in histological sections of Brca1 mutant mouse mammary glands and tumors, we found MRC2 is expressed at low level in the basal cells and highly expressed in the tumor cells." (PMID 34815798, 2021).
tumor (continued). "BRCA1 and BRCA2 are human tumor suppressor genes located on the long arm of chromosomes 17 and 13, respectively." (PMID 34198652, 2021). "A report on the outcomes of 1211 men undergoing active surveillance, including 11 BRCA1, 11 BRCA2 and 5 ATM germline carriers, has shown that BRCA2 carriers are more likely to undergo a tumour grade re-classification in subsequent biopsies." (PMID 33106584, 2021). "UWB.289/BRCA1+/−44 and UWB.289/53BP1−/− were developed from BRCA1MUT UWB.289 primary tumor cultures (derived from a gBRCA1MUT HGSOC patient) and demonstrated an increase an IC50 about 83-fold and 4-fold, respectively, compared with UWB.289 parental." (PMID 32709856, 2020). "The concordance of BRCA1 deletions and BECN1 deletions between tumor types is expected from their close proximity on chromosome 17." (PMID 31923184, 2020). "BRCA1 and BRCA2 are tumor-suppressor genes that code for proteins involved in homologous recombination (HR) repair." (PMID 33302444, 2020). "Exploitation of the synthetic lethal relationship between defects in BRCA1 and BRCA2 tumour suppressors and with RAD52 depletion or inhibition has opened many new questions into the role of the RAD52 protein in genome maintenance." (PMID 31799622, 2020). "Of the eight genes we identified, three genes (RNF7, NPEPPS, and NCCRP1) were down-regulated and the remaining five (BRCA1, TRIM37, RNF25, CDC27, and UBE2H) were up-regulated in tumor tissue compared to normal pancreatic tissue." (PMID 33414811, 2020). "Germline and acquired BRCA1 and BRCA2 alterations represent the most typical genetic alterations that determine a condition of HRD, leading to the inactivation of these tumor suppressors." (PMID 32210163, 2020). "In the current study, we found that the five differential expression genes (NFBD1, BRCA1, BRCA2, RPA1 and RAD51) were involved in NPC radioresistance, which was further validated in CNE2-RR cells, tumor xenografs and NPC patients." (PMID 32015678, 2020). "The BRCA1 and BRCA2 tumour suppressor genes play an important role in DNA damage repair to prevent the development of tumours." (PMID 32328196, 2020). "Among the eight genes, five genes (BRCA1, TRIM37, RNF25, CDC27, and UBE2H) were significantly upregulated and three genes (RNF7, NPEPPS, and NCCRP1) were significantly down regulated in the tumor tissues." (PMID 33414811, 2020). "MDSCs and TAMs are key components of the tumor‐associated microenvironment that promotes tumor progression and metastasis.[qv: 31,32] MDSCs rather than other myeloid cells, such as neutrophils and monocytes/macrophages, significantly increased in Brca1 mutant MG, but not in Brca1 mutant tumor." (PMID 32195105, 2020). "Gene expression analysis of 4 genes (BRCA1, CUL4A, ERCC1, and ERCC5), involved in the DNA damage repair (DDR) machinery, was performed in 66 surgical tumor samples." (PMID 32365979, 2020). "It is worth noting that BRCA1 was also upregulated in WT OP patients and HPV+ tumours (29.5% and 29.6%, respectively)." (PMID 32684626, 2020). "As BRCA1, also BRCA2 plays an important role in tumor suppression and DNA repair process, probably for its direct interactions with Rad51 during homologous recombination in two different domains: the eight BRC repeat and DBD domain." (PMID 32438681, 2020). "The in vivo anti-tumor effect of MLN4924 and cisplatin alone and in combination was evaluated in a NOD-SCID xenograft mouse model using BRCA1-wild type MDA-MB-231 cells." (PMID 32166000, 2020).
tumor (continued). "Studies on pathological splicing mutations support the importance for DAZAP1 in RNA splicing of several key tumor suppressors, such as NF1, BRCA1 and ATM38." (PMID 32308763, 2020). "In this study, both WEE1 and BRCA1 were found to be up‐regulated by enhanced TFAP2C mRNA stability and they drove tumour growth in vivo." (PMID 32857912, 2020). "As an autosomal dominant tumor suppressor gene, the gene of BRCA2 or BRCA1 contribute to the repair of DNA." (PMID 32571290, 2020). "For instance, intron 2 of BRCA1 DNA repair associated (BRCA1) and intron 2 of its pseudogene PsiBRCA1 can be exchanged by recombination, transferring BRCA1 into a “nonfunctional” gene without a tumor suppressive effect 59, which constitutes a new mechanism for inactivating antitumor genes." (PMID 32042317, 2020). "Recently, we have discovered a tumor-promoting role of BRCA1 in GBM, in supporting tumor cell fitness and growth through protection from endogenous replication stress via transcriptional upregulation of RRM29." (PMID 32948765, 2020). "BRCA1 and breast cancer 2 (BRCA2) are tumor suppressor genes that control aberrant cell proliferation and prevent tumor development." (PMID 33680920, 2020). "Our study provides evidence that BRCA1 and ZBRK1 possess an additional role in tumor suppression, regulating the aspartate metabolism through transcriptional repression of GOT2." (PMID 30714292, 2019). "They analyzed blood and tumor tissue from 154 patients with HGSOC and among 20 patients harbouring WBC BRCA1 methylation, 14 of them (70%) revealed methylation of the tumor DNA as well." (PMID 31225507, 2019). "The BAP1 protein contains binding domains for BRCA1 and BARD1, enzymes that form a heterodimeric complex that functions as a tumor suppressor." (PMID 31382494, 2019). "To determine the level of tumor-infiltrating immune cells, we examined CD3+ T cells and F4/80+ macrophages in tumors from KPC, Palb2-KPC, Brca1-KPC, and Brca2-KPC animals." (PMID 31877165, 2019). "Copy losses were also commonly observed for key tumor suppressors relevant to mCRPC biology, including GRHL2, ZFHX3, FGFR2, NCOR1, PHLPP1, and BRCA1." (PMID 31136607, 2019). "BRCA1 has a tumor suppressor role, which is likely to be under control via the BARD1-BRCA1 heterodimer, and ubiquitination-dependent pathways are involved in BRCA1 degradation." (PMID 30975222, 2019). "BRCA1 and BRCA2 are two genes involved in homologous recombination (HR)-mediated repair of DNA double strand breaks and have first been described as tumor suppressor genes in hereditary breast cancer." (PMID 31549213, 2019). "Almost half of recurrent IDHWT tumours (43%; 3/7) harboured at least one potentially actionable variation in the genes EGFR (14%; 1/7), PTEN (14%; 1/7), BRCA1 (14%; 1/7), BRCA2 (14%; 1/7), and ATM (14%; 1/7)." (PMID 32082376, 2019). "Conversely, miR-205-5p downregulation increased BRCA1 and RAD17 messenger RNA (mRNA) levels, leading to a reduction in in vivo tumor growth." (PMID 31514456, 2019).
tumor (continued). "Such genes include DNA repair genes (BRCA1, PCNA), a regulator of oxygen homeostasis (HIF1-alpha), anti-apoptotic genes, tumor suppressors, genes of the Akt/mTOR signaling pathway and vascular endothelial growth factor A (VEGFA)." (PMID 31205871, 2019). "Both BRCA1 and BRCA2 are tumour suppressor genes, and their functioning proteins have major roles in DNA double-strand break repair through homologous recombination (HR)." (PMID 31064392, 2019). "UHRF1 is also associated with epigenetic silencing of various tumor suppressors and other tumor-related genes, including CDKN2A, RB, BRCA1, RASSF1, PPARG, APC, CDH1, and RGS2." (PMID 31064417, 2019). "While it cannot be excluded that MYC overexpression reshapes evolution of BRCA1-deficient TNBCs via negative selection of tumor cell clones with high levels of CNAs, amplifications of MCL1 might be particularly selected for as they may counteract the pro-apoptotic effects of MYC overexpression." (PMID 30674894, 2019). "Increased levels of PD-1 and PD-L1 expression on tumor-infiltrating immune cells as compared to homologous recombination proficient tumors indicates that PD-1/PD-L1 inhibitors may be more effective in BRCA1/2-mutated rather than in the homologous recombination proficient HGSOC." (PMID 31109041, 2019). "A total of 547 genomic alterations (including 529 somatic alterations and 18 germline alterations of BRCA1/2) were detected in these 88 HGSOC tumors, with an average of 6.2 alterations per tumor (range 1‐15)." (PMID 31124283, 2019). "BRCA1 and BRCA2 are two well-characterised tumour suppressor genes involved in DSB repair by homologous recombination." (PMID 30060743, 2018). "Out of 18 OS tumour cell lines assessed, only LM7 demonstrated profound sensitivity to PARPi of a scale similar to that seen in BRCA1 mutant SUM149 cells." (PMID 30006631, 2018). "Tumor BRCA1/2 testing is more challenging than germline testing as the majority of samples are formalin‐fixed paraffin embedded (FFPE), the tumor genome is complex, and the allelic fraction of somatic variants can be low." (PMID 29215764, 2018). "In contrast, BRCA1 and BRCA2 were expressed in both the cytoplasm and the nuclei of the tumor cells." (PMID 29784019, 2018). "In this study, we found that BRCA1 plays an important role in TGF-β1 mediated chemotherapy resistance and tumor growth." (PMID 30594239, 2018). "We also compared PIN1 levels in mouse Brca1 tumor cells and normal mouse mammary epithelium and confirmed that PIN1 levels were significantly higher in the tumor cells." (PMID 30590041, 2018). "BRCA1 and BRCA2 breast tumor suppressor proteins play important roles in DNA damage response and repair, maintenance of genome stability and tumor suppression." (PMID 29718910, 2018). "Of the 9 responses in the BRCA1/2-aberrant population, two were radiological, 6 were CA125 tumour marker response, and one was both radiological and CA125 response." (PMID 29298688, 2018). "Further, due to the lack of a proper model system, i.e. ER-negative BRCA1-deficient tumor cells that can be induced by estrogen to EMT in vitro and in vivo, it is unknown if estrogen-activated EMT in ER negative BRCA1-deficient tumor cells is dependent on AKT activation." (PMID 29996906, 2018). "Aberrant methylation of three genes (BRCA1, MGMT, and MLH1), playing important roles in the different DNA repair mechanisms, were dependent on the tumor subtype and represent powerful biomarkers for precision therapy." (PMID 29882921, 2018).